TLR4 (toll like receptor 4)
Diseases named in the same sentence as TLR4 in open-access papers (continued):
Sharing a sentence is not in itself a finding about the gene and the disease.
Obesity (continued). "Flier and colleagues also found that female C57BL/6 mice lacking TLR4 and fed a high fat diet developed increased obesity, but are partially protected from insulin resistance through a mechanism involving reduced inflammatory gene expression (including IL-6)." (PMID 30666212, 2018). "Furthermore, animal models of obesity have established that fatty acid mediated alterations in TLR2 and TLR4 signaling play a central role in the establishment of insulin and leptin resistance." (PMID 30131724, 2018). "Activation of TLR4 signal transduction and induction of endoplasmic reticulum stress (ERS), are regarded as two of the most important mechanisms triggering the inflammatory activity related to obesity." (PMID 29678181, 2018). "While this study shows that neither Tlr4 and Cd14 have a role in the HFD-induced obesity HFD has the potential to influence obesity development through Tlr4 and Cd14 independent pathways." (PMID 30353127, 2018). "The potential contribution of TLR4 pathways in mediating adverse neural outcomes of obesity has not been well addressed." (PMID 30396359, 2018). "Mice lacking TLR2 and TLR4 genes do show however that TLRs are involved in the development of obesity." (PMID 28883915, 2017). "Another important issue that may activate proinflammatory potential in obesity is an increase of expression of Toll-like receptors (TLR2, TLR4) on the membranes of various cell types, such as immune and resident non-immune cells, including adipocytes in VAT." (PMID 28103807, 2017). "During the development of obesity, dysbiosis in gut microbiota increased the production of LPS mainly in the HFS group, which could activate TLR4 and promote the induction of NF-κB, provoking the expression of inflammatory cytokines and ROS production." (PMID 28420148, 2017). "While the obesity-related increase in circulating FFA promotes the development of hepatic steatosis and insulin resistance, the precise molecular mechanisms involved in the interplay among FFA, TLR4 and NOX2 have not been fully understood." (PMID 29269727, 2017). "The involvement of toll-like receptor 4 in the development of NASH was supported by a study showing that the feeding of a high fat diet did not induce obesity, insulin resistance, or inflammation in toll-like receptor 4 knockout mice." (PMID 27847552, 2016). "The present study evaluated the response of newly diagnosed NAFLD patients with or without obesity to the metformin effect in the context of the monocyte TLR4 level and production of pro-inflammatory cytokines." (PMID 26930651, 2016). "In obesity, the adipocyte is saturated with TAG, resulting in increased circulating TAG and fatty acids, the latter of which is a ligand for the pattern recognition receptor, Toll-like receptor-4 (TLR4)." (PMID 26956558, 2016). "We found that metformin decreased the TLR4 level and pro-inflammatory response in all NAFLD patients; however, its efficacy depended on their health and phenotype status at the beginning of the study, in particular the presence of obesity." (PMID 26930651, 2016). "Remarkably, we reported that the lack of TLR4 signaling improves glucose and lipid metabolism, and protected from obesity development and premature atherosclerosis." (PMID 26921251, 2016). "This increase in plasma LPS induced bya high-fat diet suggests metabolic endotoxaemia, which is considered to trigger thedevelopment of obesity, inflammation, insulin resistance, type 2 diabetes andatherosclerosis via activation of the CD14/Toll-like receptor 4 complex by LPS and/or fattyacids." (PMID 26090097, 2015). "In obesity mouse models, TLR4 is known to be involved in the inflammatory response that culminates in insulin resistance and metabolic dysfunction as demonstrated when comparing wild-type to CD14−/− mice, and to TLR4−/− mice." (PMID 26161548, 2015). "Thus, many studies have investigated the role of TLR4 and nod-like receptor protein 3 (NLRP3) in knockout mouse models in HFD-induced obesity." (PMID 26779183, 2015).
Obesity (continued). "Such increase in TLR4 expression was not connected directly with the obesity or MS, as groups with lean patients and obese without MS also had elevated level of TLR4." (PMID 26629827, 2015). "Apart from an increase in liver TLR4 mRNA in both CL and SL groups at 3 days high fat diet, there were no significant changes in peripheral indicators of obesity or inflammation in the tissues we examined." (PMID 25628527, 2014). "Resistin-induced SDF-1 upregulation by activation of TLR4, p38 MARK and NF-κB may explain a new role of resistin in the link of obesity and gastric cancer." (PMID 24929539, 2014). "In rodent models, absence of TLR4 confers protection against diet-induced obesity, insulin resistance and atherosclerosis." (PMID 23497455, 2013). "We recently identified the Radioprotective 105 (RP105)/myeloid differentiation (MD)-1 complex as a key regulator of diet-induced chronic inflammation in adipose tissue, obesity and insulin resistance that appear to be independent of the TLR4-dependent pathway." (PMID 24064574, 2013). "FFA is also an endogenous ligand for TLR2 and TLR4 which play important roles in the pathogenesis of noninfectious, inflammatory diseases of host deregulation such as obesity." (PMID 22675336, 2012). "Our findings suggest that diets high in TF induce obesity, hyperglycemia, insulin resistance, hypercholesterolemia, and hyperleptinemia even in the absence of functional TLR4." (PMID 21314942, 2011). "Recently the toll-like receptor 4 (TLR-4), that plays an important role in innate immunity through its ability to recognize bacterial lipopolysaccharides, has been postulated to play a role in the obesity-induced inflammatory response." (PMID 20508843, 2010). "Therefore, because obesity is a state of chronic inflammation that is associated with increased expression of TLR2 and TLR4, we also tested the hypothesis that activation of TLR2 and TLR4 in adipocytes represents a mechanistic link between inflammation and downregulation of adiponectin receptors." (PMID 19348674, 2009). "TLR/MyD88 is a classic signaling inflammatory response that also involves in obesity development and is inhibited by the overexpression of PPARγ via the negative control of the expression of TLR4, and then activates the expression of CD36 for promoting fatty acid uptake and fat accumulation." (PMID 40045630, 2025). "Notably, berberine can promote the differentiation of brown preadipocytes via the AMPK-PRDM16 axis, inhibit TLR4/TNF-α-mediated inflammatory responses, and reduce the expression of iNOS and COX-2, thereby enhancing thermogenesis and alleviating obesity through improved inflammation." (PMID 40362407, 2025). "TLR-4 activation stimulates JNK, which, in turn, promotes the production of cytokines, including interleukin (IL)-1, interleukin (IL)-6, tumor necrosis factor (TNF)-a, chemokines, and other proinflammatory compounds (Hypothalamic Inflammation and Gliosis in Obesity)." (PMID 37764744, 2023). "Interestingly, in mice, the absence of TLR2 and TLR4 from the plasma membrane protects against obesity and IR, which generated a lot of interest in the TLRs as possible therapeutic targets in the fight against obesity and IR." (PMID 37513660, 2023). "In protocol II, we evaluated whether blocking TLR4 with eritoran reverses baseline measures of insulin resistance in nondiabetic individuals with obesity." (PMID 36066991, 2022). "However, the role of hypothalamic astrocyte TLR4 signaling in inflammation and obesity is not clear in humans." (PMID 36188456, 2022). "Pharmacologic inhibition of TLR4, TLR4 knockout, TLR4-interactor knockdown, or hypothalamic ARC-restricted TLR4 knockdown reduces food intake, increases whole-body energy expenditure, reduces hypothalamic inflammation, and protects rodents from HFD-induced obesity." (PMID 36188456, 2022).
Obesity (continued). "This evidence shown TLR4 in non-neuronal cells may affect the function of neurons in hypothalamus and potentially make a contribution of appetite and obesity." (PMID 34899611, 2021). "Besides hyperglycemia, elevated levels of saturated fatty acids (SFA), e.g., palmitate, have been postulated to contribute to islet inflammation and β-cell dysfunction and proliferation in the context of obesity and T2DM through a toll-like receptor 4 (TLR4)-mediated mechanism." (PMID 32709161, 2020). "Also, activation of TLR2 (Pam3Cys) or TLR4 (LPS), which has been shown to occur in obesity, has no outspoken effect on glycerol secretion." (PMID 32849273, 2020). "Besides, in our study, we investigated the non-canonical pathway of TLR4 involving IKKε in the hypothalamus and in parallel the canonical pathway seems to have a significant effect on the development of obesity." (PMID 32576879, 2020). "Microbial dysbiosis and damage to the integrity of the colonic barrier may induce translocation of bacterial products, such as lipopolysaccharide (LPS), into the blood, which may result in activation of Toll-like receptor 4 (TLR4) and lead to inflammatory responses, insulin resistance, and obesity." (PMID 33302947, 2020). "Moreover, we recently found that IMD in PVN attenuates TLR4-mediated ERK activation and sympathetic excitation in rats with obesity-related hypertension, which suggests that IMD may inhibit Ang II-induced ERK activation." (PMID 31466304, 2019). "Obesity seems to disturb this scenario; after 6 weeks of HFD, bone marrow malfunction is induced by a mechanism depending on LPS originated from bacteria (translocated from the gut to the bloodstream) that stimulate, via TLR4, myelopoiesis instead of lymphopoiesis." (PMID 31616626, 2019). "Fatty acids may activate Toll-like receptor 4 (TLR4) signaling in adipocytes and macrophages and induce inflammatory signaling, and mice lacking TLR4 were shown to be protected against high-fat diet-induced obesity and insulin resistance." (PMID 30983955, 2019). "Multiple TLRs, including TLR2, TLR3, TLR4, TLR5, TLR8, TLR9, and TLR10, have been indicated in the regulation of PAMPs from gut microbiota and DAMPs from metabolic stress and tissue damage, which initiate the inflammatory responses contributing to the development of obesity-related chronic diseases." (PMID 31582899, 2019). "Though TLR4 is well established as mediating the effects of saturated fatty acids on adverse outcomes in metabolic measures and inflammation, its regulation of obesity-related changes in brain have not been thoroughly investigated." (PMID 30396359, 2018). "We conclude that HFD induced obesity in C57BL/6 mice can lead to the occurrence of OA, and oral resveratrol may alleviate OA pathology by decreasing the levels of cytokines and/or through inhibiting TLR4/TRAF6 signaling pathways." (PMID 28250578, 2017). "However, spinal TLR4 expression has not been studied in a model of obesity-induced visceral hypersensitivity." (PMID 27159520, 2016). "Whereas the changes in TLR2/TLR4 expression in the adipose tissue are regarded as important actors in metabolic inflammation, the changes in the adipose tissue expression of endocytic TLR8 in obesity/T2D remain unclear." (PMID 27980459, 2016). "However, the relationship between TLR4 and cell signaling proteins, obesity and metabolic syndrome is not completely established." (PMID 26635627, 2015). "Apart from being involved in recognition of lipopolysaccharide, a constituent of gram negative bacteria cell wall, TLR4 can recognize endogenous ligands such as saturated free fatty acids thereby creating a direct link between the innate immunity and diet-induced obesity and insulin resistance." (PMID 24594974, 2014). "Therefore, because TLR2 and TLR4 are activated in adipose tissue in obesity, the induction of SLPI in adipose tissue during obesity may be influenced by the activation state of the TLRs." (PMID 21356117, 2011).
Obesity (continued). "However, unlike RAGE, TLR4 protein abundance was not affected by obesity or AE." (PMID 37675469, 2023). "Indeed, TLR4 inhibition in THP-1 macrophages significantly ameliorates asprosin-induced pro-inflammatory effects, a finding which merits further research attention given the well-established role of chronic inflammation in obesity and obesity-related complications." (PMID 36613673, 2022). "Further exploration of FA effects on TLR4/NF-κB signaling and NLRP3 inflammasome–induced pyroptosis and the relationship between the two signaling pathways, may help to elucidate the roles of different FA mechanisms in OA, revealing possible intervention targets for obesity-related OA." (PMID 35571243, 2022). "Therefore, the potential therapeutic strategy for obesity-related OA could be by inhibiting the leptin signal via the reduction of leptin levels and enhancement of SOCS3 expression, or by directly suppressing TLR4 expression." (PMID 34457118, 2021). "In this regard, it is possible to assume that elevated TLR4 expression in the hypothalamus may be due, at least in part, to exposure to PM2.5 and that a deletion of TLR4 before exposure to PM2.5 could protect mice from the development of leptin resistance and obesity." (PMID 32576879, 2020). "Indeed, mice lacking TLR-4 are protected against high-fat diet-induced obesity, inflammation, and insulin resistance because they are resistant to the suppression of insulin signaling during lipid infusion and exhibit reduced insulin-mediated changes in systemic glucose metabolism." (PMID 27881903, 2016). "Our data are in agreement with a previous study revealing blunted HFD-induced adipose and liver inflammation and ameliorated obesity-induced adipose and liver insulin resistance but no improvement in skeletal muscle insulin sensitivity in mice with haematopoietic cell-specific deletion of TLR4." (PMID 24203314, 2014). "Thus, both TLR4 and TLR2 could participate in the sensing of abnormal levels of nutrients, especially fatty acids and in the detection of gut microflora modification in obesity." (PMID 23316186, 2012). "However, other studies have described a higher feeding efficiency of the C3H/HeJ mice with increased adipose tissue mass and adipocyte hypertrophy, an increase in body weight gain and adipose tissue mass in female TLR4−/− mice or no protection against obesity in male TLR4−/− mice." (PMID 23316186, 2012). "Additionally, obesity has been connected to an overgrowth of Gram-negative bacteria, resulting in elevated levels of lipopolysaccharides (LPS) within the gut, which impair its barrier function and thereby induce systemic inflammation via Toll-like receptor 4 (TLR4) signaling." (PMID 41007770, 2025). "Using this serum, the authors observed an increase in TLR4, but not NOD2 ligands in mice with obesity." (PMID 40635891, 2025). "One of the rest significant questions in regard to the relationship between IVDD and obesity is how the PKR response to the hypertriglyceridemia and links the obesity to NP cell pyroptosis since TLR4 is not indispensable for PKR activation." (PMID 41163024, 2025). "Moreover, oral gavage with 109 CFU/200 μL A. muciniphila reverses high fat obesity through improving intestinal barrier integrity, inflammation, energy balance, and triglyceride and glucose in the blood, which also suppresses mRNA expression of Tlr4 and Il-6 but not Tnf-α in adipose tissues." (PMID 37287985, 2023). "However, the effects of CD44 on obesity may be independent of TLR4 signaling." (PMID 35410390, 2022). "Enhanced S100β levels, suggestive of reactive gliosis, have been shown during absence of TLR4 or TLR2 signaling, enteric dysbiosis, diet-induced obesity, impaired mitochondrial respiration, mechanical nerve injury." (PMID 33923250, 2021). "Mice lacking Toll-like receptor 4 (TLR4) (endotoxin receptor) were significantly resistant to developing characteristics of HFD-induced metabolic syndrome, such as obesity and insulin resistance." (PMID 33922125, 2021).
Obesity (continued). "Together these data argue that LPS, which acts via the TLR4/CD14 receptor complex, does not play a role in HFD-induced obesity." (PMID 30353127, 2018). "The lack of any measurable differences in body weight or body fat gain seen in Cd14−/− mice, compared to Wild-Type or Tlr4−/− mice, suggests that TLR2 signalling is unlikely to have a role in diet-induced obesity." (PMID 30353127, 2018). "Specifically, cell-intrinsic TLR4 is required for LKSneg and CLP malfunction during stages of obesity when gross BM inflammation is not readily detectable." (PMID 29453396, 2018). "PC significantly decreased the TLR4 level in group I and III but not in group II thus indicating also the role of obesity in high cytokines' response ex vivo to LPS treatment." (PMID 26629827, 2015). "However, there were no obese female TLR4−/− mice, and only 3% of the male TLR4−/− mice reached the obesity criterion." (PMID 38275739, 2024). "Our study showed that with the presence of AG490, leptin could not affect the expression of TLR4 and other inflammatory-related proteins which suggested that leptin may regulate TLR4 expression through the JAK2-STAT3 pathway in obesity-related OA." (PMID 34457118, 2021). "However, sex, sexual steroids, and obesity did not influence TLR2 and TLR4 expression postprandially, despite obese subjects, chiefly men, showing higher fasting TLR2 levels than non-obese individuals." (PMID 31936430, 2020). "TLR4 knockout mice fed with a high-sugar and HFD did not develop obesity and insulin resistance." (PMID 33551809, 2020). "However, obesity and sex hormones showed opposite influences on surface expression of TLR2 and TLR4, but not on their gene expression, pointing to regulatory posttranscriptional mechanisms." (PMID 31936430, 2020). "Accordingly, CD14-deficient mice do not become obese on a high-fat diet and do not develop obesity-related pathologies such as insulin resistance and cardiovascular complications; these phenomena are CD14-dependent but TLR4-independent." (PMID 23898465, 2013). "In particular, a HFD led to an upregulation of genes such as toll-like receptor 4 (TLR4), NF-κB, Cd68, Emr1, IL-6, indoleamine 2,3-dioxygenase (IDO), TNF-α, and interferon gamma (IFN-γ) in rodents, suggesting that these changes were related to diet-induced changes rather than obesity." (PMID 31731503, 2019). "Finally, epigenomic profiling via CUT&Tag reveals differential H3K4me3 enrichment at key inflammatory and myeloid differentiation loci, including Tlr4 and E2F targets, which may contribute to the heightened inflammatory responsiveness of HSPCs for nonresolving myelopoiesis in HFD-induced obesity." (PMID 40795290, 2025).